MMP1 (matrix metallopeptidase 1)
Diseases named in the same sentence as MMP1 in open-access papers (continued):
Sharing a sentence is not in itself a finding about the gene and the disease.
cancer (continued). "To a lesser extent, we could note the presence of IL8, TIMP1 and MMP1 (Cancer group) that shared these characteristics." (PMID 28962550, 2017). "However, limited studies investigated the involvement of MMP1 in drug responses of the cancer cells." (PMID 28334049, 2017). "It remains unknown why and how cancer cells package MMP1 mRNA in EVs; nevertheless, it is conceivable that the use of EVs may offer an effective strategy for cancer progression." (PMID 28262727, 2017). "As a result, a broad range of MMP1 expression was detected across the samples, including control, low potential malignancy and cancer (left), and the percentage of MMP1-high population in cancer patients (27%) was comparable to that in The Cancer Genome Atlas database." (PMID 28262727, 2017). "Therefore, we further investigated the functional role of MMP1 in drug responses of the cancer cells." (PMID 28334049, 2017). "To determine whether MMPs play an important role in STS-mediated cancer cell invasion, we investigated the expression of MMP-1, MMP-2, and MMP-9 mRNA in PC-3 or HeLa cells expressing STS after exposure to STX-64." (PMID 28977889, 2017). "We also found higher amounts of MMP1 mRNA in patients before chemotherapy than after chemotherapy, thus suggesting that chemotherapy reduced the secretion of malignant EVs from cancer cells, or that the cancer volume simply decreased." (PMID 28262727, 2017). "Previous studies mainly focused on the role of MMP1 in cancer cell growth, invasion and metastasis." (PMID 28334049, 2017). "In conclusion, our results provide evidence that candidate pathogenic genes such as MMP1, CDC45, and CAT and their enriched pathways, respectively, of pathway in cancer, cell cycle, and methane metabolism might be involved in the pathogenesis of CC." (PMID 27034707, 2016). "Importantly, MSH6, PTGS2, HDAC1, JUN, SLC2A1, and MMP1 were enriched in the pathway in cancer, of which MSH6 and MMP1 were candidate genes." (PMID 27034707, 2016). "Our results also suggest that MMP1 has a strong ability to promote cancer invasion and metastasis." (PMID 27995036, 2016). "Since MMP1 is located outside the cell, this makes it a prime anti-cancer target." (PMID 26513020, 2015). "Increased MMP-1 gene expression appears to be a biomarker for cancer metastasis." (PMID 25191698, 2014). "In addition, three putative targets (MMP1, MMP2, and MMP7) of marketing anti-cancer drugs were reported to be associated with NSCLC." (PMID 24429698, 2014). "In this review, we examine the expression pattern of MMPs in HNSCC by microarray datasets and summarize the current knowledge of MMPs, specifically MMP-1, -3, -7 -10, -12, -13, 14 and -19, that are highly expressed in HNSCCs and involved cancer invasion and angiogenesis." (PMID 24531055, 2014). "The present authors hypothesized that the degradation of ECM by MMP-1 might be involved in the process of cancer cell invasion." (PMID 24978432, 2014). "Otherwise, as recently reported in human cancers, Wnt5a/Ror2 signaling may up-regulate the expression of matrix metalloproteinases (MMPs) such as MMP1, MMP2, and MMP13 to increase cell invasiveness." (PMID 25211363, 2014). "Some of the upregulated genes are related to CSC/’cancer stemness’ such as CXCR4, CD133, EPCAM and SOX9, while others are associated with apoptosis (FASLG, TJP2, DUSP4), the MAPK pathway (MAP2K4, DUSP4), and chemoresistance (MMP1, an ETS1 target gene)." (PMID 24069258, 2013). "Fifth, the genes were previously associated with human cancers, in particular MAGEA12 however only DISCS LARGE (DROSOPHILA) HOMOLOG-ASSOCIATED PROTEIN 5 (DLGAP5) and MATRIX METALLOPEPTIDASE 1 (MMP1) have been previously reported to be up-regulated in HCC tumors." (PMID 23950870, 2013). "It has been shown that matrix metalloproteinase-1 (MMP-1) causes activation of PAR1 leading to expression of the pro-angiogenic secreted chemokines CXCL8 (IL-8), CXCL1 (GRO-α), and CCL2 (MCP-1) by the cancer cells." (PMID 24384839, 2013).
cancer (continued). "Previous studies have also shown that MMP-1 is an important mediator in cancer metastasis." (PMID 23892595, 2013). "Furthermore, the present study verified the expression of the cancer invasion-related genes, MMP-1, MMP-2, EGFR and COX-2, which were upregulated in the CD44+ GC cells, indicating a capacity to manipulate cancer invasion and even metastasis." (PMID 23833643, 2013). "Knocking down HIF-1α, which leads to MMP-1 upregulation, might contribute to the degradation of the extracellular matrix of the peritoneum, allowing the invasion of cancer cells and the formation of peritoneal metastasis." (PMID 23181099, 2012). "Like the related invadopodia described in other cancer cells, the podosomes are actin-rich structures closely associated with adhesion molecules and ECM-degrading enzymes such as the matrix metalloproteinases MMP-1, MMP-2 or MMP-9." (PMID 20152043, 2010). "Nishiota showed MMP-1 is expressed more strongly in the cancer front of invasion." (PMID 15740610, 2005). "Additionally, c-JUN was found to regulate the expression of MMP1, a known mediator of cancer invasiveness, and MAP4K4, creating a feedback loop that may enhance metastatic potential." (PMID 39990663, 2025). "The fact that CAFs treated with siRNA directed against MMP-1 continued to shield cancer cells from cetuximab therapy suggests that either several MMPs may work together to promote resistance, or that a different MMP family member underlies the protective effect." (PMID 37055382, 2023). "Besides, MMP1 also increased stemness of cancer cells which may be another possible mechanism for MMP1-induced chemoresistance." (PMID 37484321, 2023). "However, there is less research on the regulation of MMP1 in the cancer acidic microenvironment." (PMID 35414794, 2022). "Therefore, targeting MMP1 is considered an essential step for suppressing cancer progression." (PMID 34445346, 2021). "Moreover, as the conjugate material displays autofluorescence and endocytosis, it might be used to diagnose cancers with a high concentration of MMP-1 in the future." (PMID 35010011, 2021). "Moreover, EVs with MMP1 mRNA in cancer ascites induces apoptosis of mesothelial cells." (PMID 34907282, 2021). "Notably, MMP1 also was assigned to the “pathways in cancer” from the KEGG database." (PMID 33046043, 2020). "In addition, co-transfection of MDA231-TGL cells with miR-202-3p and MMP1 siRNA rescued the effect of miR-202-3p inhibition on the transmigrative abilities of cancer cells and restored normal TEER values and junctions expression similar to the control group in the brain endothelium." (PMID 33002044, 2020). "It has been shown that high levels of PUFAs and a very high n-6/n-3 ratio may contribute to the increased incidence of cancer via upregulation of matrix metalloproteinase-1 (MMP-1) and that the decreased n-6/n-3 fatty acid ratio downregulates the expression of MMP-1." (PMID 30965590, 2019). "Therefore, this could be why carcinoma cells have less incidence of lymphatic or vascular invasion despite high expression of MMP-1, but this question requires further investigation for clarification." (PMID 29463039, 2018). "Available FADD and caspase-8 may recruit and stabilize TRAF2 (and perhaps other unknown proteins), resulting in the activation of ERK and JNK signaling and subsequent AP-1-dependent expression and activation of MMPs (e.g., MMP1) and final promotion of invasion and metastasis of cancer cells." (PMID 26510914, 2015). "The upregulation of gene products associated with migration and invasion (osteopontin, MMP1, vimentin, filamin-A, and β-actin) and gene products for extracellular matrix molecules and their modulators (fibronectin, collagen, ITGBL1, and MXRA5) reflects the invasive nature of this cancer." (PMID 25861239, 2015). "Thus MMP1 can be responsible for more invasive phenotype of drug-resistant cancers." (PMID 24804215, 2014).
cancer (continued). "However, although these studies indicate the importance of MMP-1 expression in cancer malignancy, the detailed mechanism of MMP-1 in HNSCC progression is still unknown." (PMID 24531055, 2014). "Real-time PCR revealed significantly higher expression of the three most prominent cancer related MMPs—MMP1, MMP2 and MT1-MMP—in WM266-4 cells compared to 501mel cells, suggesting that during cooperative invasion, WM266-4 cells could adopt a role similar to fibroblasts." (PMID 25066122, 2014). "Therefore, MMP-1 might be the BDNF-responsive mediator, which causes the degradation of the ECM, resulting in subsequent cancer migration and invasion activity." (PMID 23892595, 2013). "However, other studies showed a negative association between MMP-1 polymorphisms and cancer susceptibility." (PMID 22655095, 2012). "Intriguingly, high MMP1 expression has been reported in a rare and aggressive NSCLC subtype called large cell carcinoma, which is rich in both poorly differentiated cancer cells and senescent CAFs that upregulate many pro‐inflammatory factors." (PMID 40908670, 2025). "This chemokine then binds CXCR2 receptors on cancer cells, inducing MMP1 production in the TME and enhancing cancer cell migration and invasion." (PMID 41445742, 2025). "MMP1 degrades the ECM, removing physical barriers that impede cancer cell migration into surrounding tissues and infiltration into blood and lymphatic vessels, ultimately accelerating cancer metastasis." (PMID 40872572, 2025). "The anti-proliferative effects of C. sativa DCM are mainly attributed to the modulation of key molecular pathways, including the inhibition of SOD activity and GSH level, as well as the suppression of MMP-1, MMP-9, and TGF-β in both cancer cell lines." (PMID 41516029, 2025). "Of note, co‐stimulating normal pulmonary fibroblasts with MMP1 and TGF‐β1 was sufficient to elicit a senescent‐like phenotype, revealing a novel pathologic function of excessive MMP1 production in cancer." (PMID 40908670, 2025). "Our findings are consistent with previous studies indicating that drug-resistant cancer cells are more prone to undergo EMT, thereby highlighting the critical role of MMP1 in this process." (PMID 40287412, 2025). "Within the constructed network, MMP1, KRT7, EGR1, and IL11 played crucial roles, likely due to the cell lines representing invasive and proliferative cancers." (PMID 41590789, 2025). "Concurrently, markers like HGF, EGF, MMP–1 and the scavenger receptor CD36 reflect processes of chronic inflammation, tissue remodeling, and metabolic reprogramming, which facilitate cancer cell proliferation and survival." (PMID 41194922, 2025). "Computational analyses also evidenced BA’s potent binding affinity with the primary cancer-related targets CA9, DHFR, and MMP1; molecular dynamics simulations validated the stability of these interactions." (PMID 41585891, 2025). "MMPs, particularly MMP1, are essential mediators in tissue remodeling, capable of degrading a diverse array of ECM components, thereby fostering cancer cell invasion and metastasis." (PMID 39551792, 2024). "Several studies have demonstrated a strong correlation between the expression of MMP-1, MMP-2, MMP-7, MMP-9, MMP-10, and MMP-12 enzymes, tumour size, cancer progression, lymphatic dissemination, and bloodstream distant metastasis (table in Section 5)." (PMID 39337393, 2024). "We validate the generality of EDS and apply it to effectively block the proteolysis of cell surface receptors in cancer (CDCP1 and EphA2) and the proteolytic activation of three proenzymes in cell migration (MMP1, MMP3, and MMP9)." (PMID 38683990, 2024). "Here, we show that those NFs, isolated from HNSCC patients, results from the cancer cells-mediated activation of STAT3, which regulates MMP1 expression that are subsequently utilized by the cancer cells." (PMID 38320998, 2024).
cancer (continued). "MMP1, MMP3, and MMP10 are highly expressed in HNSCC, compared to other cancers by analyzing the data of Oncomine and GEPIA databases." (PMID 38302910, 2024). "To further demonstrate the generality of the EDS approach, we developed highly selective blockers of the proteolytic activation to two other MMPs (i.e., MMP1, MMP3) that play roles in multiple cancers and are thought to be promising cancer targets." (PMID 38683990, 2024). "Matrix metalloproteinases (MMPs), particularly MMP13, MMP1, and MMP7, are known to play a significant role in cancer progression." (PMID 38707175, 2024). "Eight hub genes (MMP1, MMP7, MMP13, LAMC2, LAMB3, PLAU, COL7A1, and SPP1) were upregulated in both HNSCC and LSCC, suggesting a significant role in cancer progression." (PMID 38707175, 2024). "Among 36 genes, MMP1, HSP90B1, PTK2, MMP3, NOTCH1 and CDH5 had higher methylation status at pan-cancer level." (PMID 38694917, 2024). "It has been known that STAT3 and p300 can contribute to various cancer progression, and STAT3 activation (e.g., p-STAT3) can co-localize with MMP1, governing MMP1 induction in NSCLC." (PMID 38560562, 2024). "CEBPD has been identified as a regulator of MMP1, MMP3, and MMP9 in the gene profiles of cancer cells." (PMID 38419037, 2024). "In this study, the secretion of several proteases including cathepsin-B, MMP-1 and MMP-13 by cancer cells was shown to be significantly increased in response to the presence of galectin-3." (PMID 37055381, 2023). "Meanwhile, we noted that Matrix Metalloproteases (MMPs), including MMP1, MMP3, MMP7, MMP10 and MMP13 genes were significantly upregulated in the BSE group, and they were almost universally upregulated in cancer." (PMID 37697300, 2023). "Direct binding of RUNX2 to the MMP1 promoter region was detected, suggesting the potential significance of the RUNX2-MMP1 axis in cancer progression." (PMID 37108164, 2023). "For example, Metalloproteinase Inhibitor 1 (TIMP-1) inhibits Interstitial collagenase (MMP-1) canonically, but its moonlighting function activates cell proliferation and survival in cancer." (PMID 36672169, 2023). "The immunosuppressive mechanism of NA can be described as follows: NA elevated the mRNA expression of ARG2, MMP1, S100A4, and RAPSN in granulocytes, thereby inhibiting the CKA of granulocytes and promoting cancer development." (PMID 36817446, 2023). "Transcriptome sequencing analysis and qRT-PCR showed that NA elevated the mRNA expression of ARG2, MMP1, S100A4, and RAPSN in granulocytes, thereby reducing the anti-cancer function of granulocytes." (PMID 36817446, 2023). "It is interesting that a methylated derivative of quercetin effectively inhibited matrix metalloproteinase-1 (MMP-1), an enzyme involved in cancer invasion and metastasis, with a more potent effect than quercetin itself." (PMID 38068974, 2023). "Many MMP members such as MMP-1, MMP-2, and MMP-9 are overexpressed in cancer and contribute to cancer cell growth, apoptosis, angiogenesis, invasion and metastasis." (PMID 37055381, 2023). "Meanwhile, the relative expression level of MMP1, MMP3, and MMP9, related to the proliferation of cancer cells in the downstream pathway was significantly decreased." (PMID 37477531, 2023). "These signature included EGFR, COX2, and the matrix metalloproteinases 1 (MMP1), CXCL1 and IDI1 which were highly expressed in the Triple Negative subtype and HER2-positive cancers." (PMID 36761968, 2023). "The V6 (stage 7, submucosal invasion cancer stage b) proteins participated in EMT signaling and PI3K-AKT-mTOR signaling (e.g., MMP1/2, PIK3CB, etc.)were consistent with the molecular features of the submucosal invasion cancer stage in the main cohort." (PMID 36966136, 2023). "Many of the genes upregulated, i.e., MMP1, MMP13, S100A7, CEMIP, and CA9 are known to increase in various cancer cells." (PMID 36766731, 2023).
cancer (continued). "In contrast, ginsenoside Rg1 downregulated the mRNA expression of ARG2, MMP1, S100A4, and RAPSN, and upregulated the mRNA expression of LAMC2, DSC2, KRT6A, and FOSB, thereby enhancing the anti-cancer function of granulocytes inhibited by NA." (PMID 36817446, 2023). "Seven genes had lower expression in HBV+ live cancer compared with NAT samples, with LPCAT3 and MMP1 being the exceptions (P < 0.05)." (PMID 37004044, 2023). "Among these genes, MMP1 was positively correlated with PRKRA expression, and involved in cancer progression and chemoresistance." (PMID 37484321, 2023). "MMP-1 and MMP-10 primarily affect tissue integrity by degrading ECM components, thereby promoting cancer metastasis." (PMID 36980779, 2023). "Carcinoma-produced MMP1 activates neuronal protease-activated receptor 1 (PAR1) and induces substance P (SP) release, activating carcinoma neurokinin 1 receptor (NK1R), which plays a pivotal role in tumor progression and PNI." (PMID 36900158, 2023). "Out of the detected hub genes, six (CCL20, CXCL1, CXCL3, CXCL8, CXCL11, and MMP1) were among over-expressed vDEGs which have been corroborated by the GEPIA in both COAD and READ cancer types." (PMID 35333898, 2022). "As a supplement, we performed correlation analysis between MMP1 and IPS based on the cancer immunome (TCIA) database, which provides results of comprehensive immunogenomic analyses of next generation sequencing data (NGS) data for 20 solid cancers." (PMID 35948625, 2022). "Among MMPs, MMP-1, MMP-2, and MMP-9 are reported to be most commonly related to malignant tumors, their metastases, and local invasion." (PMID 36551933, 2022). "When MMP expression was downregulated using MMP-1 inhibitor and in siRNA-treated CAF, cancer cells were partially protected from the cytotoxic effect of cetuximab treatment." (PMID 35586209, 2022). "Numerous studies have reported that MMP-1, MMP-2, and MMP-9 enzymes and TIMP-1 and TIMP-2 inhibitors play an active role in angiogenesis, local invasiveness, and metastatic potential of malignant tumors." (PMID 36551933, 2022). "The stroma fibroblasts and MSC can also produce MMPs, in particular, MMP-1, MMP-2 and MMP-9 in cell culture, when incubated with the conditioned medium or directly with cancer cells." (PMID 35163805, 2022). "Several of these specialized TME microenvironments are enriched by the pan-cancer survival network, for example HIF1A signaling (p = 4.27 × 10−6; FGF2, IGF2, MMP1, MMP14, MMP3, PIK3R3, SERPINE1, TGFB1)." (PMID 35106465, 2022). "We conducted pan-cancer assays based on TCGA datasets to investigate the putative roles of GPX3, MMP1, and MMP12 in malignancies." (PMID 36081670, 2022). "The specificity was also demonstrated against MMP-1, a MMP type protein that contains PEX domain and is present in abnormal levels in different types of cancer." (PMID 36291022, 2022). "Its expression regulates matrix metalloproteinase-1 (MMP-1) and cell motility, and it correlates with increased cancer cell invasiveness." (PMID 36321045, 2022). "Collectively, our findings together with others strongly suggest that MMP1 probably functions as a pro-tumorigenic oncogene via enhancing cancer cell proliferation, migration, and invasion in HNSCC by inducing EMT and cancer-related pathways." (PMID 36105241, 2022). "Previous reports on other carcinoma cell lines showed treatment with SFN resulted in down-regulation of matrix metalloproteases, MMP-1 and MMP-2, crucial to cancer cell migration and metastasis." (PMID 34316328, 2021). "The high expression levels of MMP1 and MMP3 enhance cancer cell migration and invasion, and predict poor prognosis for NPC." (PMID 34544905, 2021). "Although MMP1, MMP10 and PTHLH were mainly up-regulated in the 21 cancer types, the other two members GATM and ARHGEF26, were primarily down-regulated." (PMID 34301206, 2021). "In detail, both ADAM12 and MMP1 expression were upregulated in 16 cancer types (p < 0.05), PLOD3 was upregulated in 17 cancer types (p < 0.05)." (PMID 34121340, 2021).